SHBG (sex hormone binding globulin)
Diseases named in the same sentence as SHBG in open-access papers (continued):
Sharing a sentence is not in itself a finding about the gene and the disease.
Insulin resistance (continued). "Furthermore, DPP4 activity was associated with all insulin resistance markers herein tested (i.e., we found direct associations with fasting insulin and HOMA-IR and inverse associations with SHBG and QUICKI)." (PMID 30886868, 2019). "Insulin resistance and hyperinsulinemia may directly stimulate production of androgens via ovarian tissue steroidogenesis by inhibiting hepatic sex hormone-binding globulin (SHBG) production, thus increasing free testosterone." (PMID 31731497, 2019). "The directional influences between serum sex hormone-binding globulin (SHBG), adiposity and insulin resistance during pubertal growth remain unclear." (PMID 30925463, 2019). "In this way, we aimed to elucidate whether increased adiposity and insulin resistance during pubertal transition predicts subsequent serum SHBG or vice versa." (PMID 30925463, 2019). "Similar researches have found that there is a negative correlation between SHBG with insulin levels, insulin resistance, and diabetes risk, and researchers believe that low serum SHBG is an independent risk factor for type 2 diabetes." (PMID 31752806, 2019). "This may explain why SHBG tends to be higher in lean individuals with type 1 diabetes, and lower in the presence of obesity with hepatic insulin resistance." (PMID 29995902, 2018). "SHBG production is negatively regulated by insulin and monosaccharides and numerous studies in men, children and adolescents have shown that SHBG levels are reduced in obesity, insulin resistance, metabolic syndrome and type 2 diabetes." (PMID 30321217, 2018). "Subsequently, the level of SHBG stabilizes and this may be attributable to the hyperinsulinemia and insulin resistance that increase progressively from the late second trimester." (PMID 28279160, 2017). "Sex hormone binding globulin (SHBG) is a marker of insulin resistance." (PMID 28458728, 2017). "Notably, SHBG levels in children and adults are inversely related to adiposity and to insulin resistance." (PMID 27462374, 2016). "This is because of the confounding effects of SHBG, itself being a strong associate of insulin resistance, and because SHBG but not T was inversely associated with worse glycaemic control." (PMID 27274996, 2016). "Sex hormone-binding globulin (SHBG), mainly secreted by hepatocytic differentiated hsubMSC, is a liver-derived plasma protein, whose low levels were associated with non-alcoholic fatty liver disease (NAFLD) and insulin resistance." (PMID 27409608, 2016). "The low SBHG levels seen in obese men at baseline are likely due to the high levels of insulin resistance and the increase in SHBG seen during the first month after bariatric surgery likely reflects the decrease in insulin resistance with rapid weight loss and caloric restriction." (PMID 27725831, 2016). "First, low sex hormone-binding globulin (SHBG) levels seen in MOSH are similar to those with metabolic syndrome and type 2 diabetes and decreased SHBG level is associated with the increase in body mass index (BMI) and insulin resistance." (PMID 27725831, 2016). "Insulin resistance and compensatory hyperinsulinemia result in an increased ovarian androgen production along with the reduction of hepatic sex hormone binding globulin (SHBG) production." (PMID 27688754, 2016). "Low SHBG level was a significant predictor of insulin resistance,low HDL-C and MetS in children." (PMID 25647406, 2015). "Hyperinsulinemia/insulin resistance may stimulate osteoblast cells activity directly and indirectly via a suppression of the production of the sex hormone binding globulin (SHBG) and the insulin-like growth factor binding protein (IGFBP)." (PMID 25245338, 2014). "This study indicated that SHBG was a well- established marker of insulin resistance in diabetics, and low levels had been reported in adolescent girls with premature pubarche (who were known to be at risk for PCOS and insulin resistance)." (PMID 25223276, 2014).
Insulin resistance (continued). "Our findings clearly demonstrated that PCOS is associated with significantly higher FAI and insulin resistance levels and decreased plasma SHBG levels, independent of body mass index." (PMID 24694334, 2014). "The prevalence of concomitant dyslipidemia, hypertension and diabetes suggests that insulin resistance may be a determinant of SHBG levels." (PMID 24714992, 2014). "Circulating SHBG had an inverse correlation with insulin resistance." (PMID 29043159, 2013). "Thus, the results of our study do not allow us to make causal inferences regarding the relationships of endocrinological hormones and SHBG with insulin resistance." (PMID 23825975, 2013). "This study supported earlier observations that a significant inverse correlation exists between SHBG and insulin resistance and provides evidence that the relationship may extend to type 2 diabetic men of African ancestry in Nigeria." (PMID 29043159, 2013). "Low SHBG and adiponectin levels suggest a post-receptor insulin signalling defect, as observed in other lipodystrophic syndromes, where ectopic fat deposition, particularly in muscle and liver, is thought to play a major role in insulin resistance." (PMID 23849162, 2013). "Insulin resistance and/or compensatory hyperinsulinemia increase the availability of both circulating androgen and androgen production by the adrenal gland and ovary mainly by decreasing sex hormone binding globulin (SHBG)." (PMID 22748101, 2012). ", Insulin resistance contributes to metabolic features but also to reproductive features through augmenting androgen production and increasing free androgens by reducing sex hormone binding globulin (SHBG)." (PMID 20591140, 2010). "SHBG and total testosterone, but not free testosterone, significantly decreased in parallel across AD quintiles, an expected finding since stepwise insulin resistance is associated with decreased levels of the androgen transporter." (PMID 21156040, 2010). "Additionally, in the presence of insulin resistance, compensatory hyperinsulinaemia usually results in reduced levels of sex hormone binding globulin." (PMID 20041184, 2009). "However, the increased prevalence of OSA could be linked to insulin resistance either directly or indirectly through factors including adiposity, with the potential mechanism of insulin resistance accompanied by hyperinsulinemia leading to low SHBG levels." (PMID 39996383, 2025). "Moreover, both thyroid function and insulin resistance reportedly affect SHBG levels." (PMID 40495241, 2025). "Similarly, the lack is a generally accepted cut-off point for SHBG, determining insulin resistance." (PMID 40430120, 2025). "On the contrary, a prospective study has indicated that basal serum SHBG is negatively associated with NAFLD development but positively associated with NAFLD regression, suggesting a more complex role of SHBG in the pathogenesis of NAFLD and insulin resistance." (PMID 40650160, 2025). "Similarly, the Study of Women’s Health Across the Nation (SWAN), which included 3297 pre- and perimenopausal women, showed that low SHBG levels and a high free androgen index value were positively correlated with insulin resistance, inflammation, and dyslipidemia." (PMID 40149685, 2025). "Insulin resistance and the resultant hyperinsulinemia are thought to play a key role linking adiposity and early puberty due to increased levels of androgens from both the adrenal glands and ovaries and decreased concentration of SHBG, resulting in an increase in bioavailability of sex steroids." (PMID 41291865, 2025). "SHBG can bind to estrogen in the plasma and directly regulate the bioavailability of estrogen and its access to target cells, whereas increased insulin resistance leads to inhibition of SHBG expression, which in turn leads to an increase in the concentration of biologically active estrogen." (PMID 38813109, 2024).
Insulin resistance (continued). "The decrease in estrogens is accompanied by a marked reduction in SHBG concentrations and an increase in the free androgen index due to the tendency of adipose tissue to accumulate, while insulin resistance and hyperinsulinemia may augment androgen secretion after menopause." (PMID 38248773, 2024). "In addition, the enhanced levels of SHBG in hemodialysis patients were inversely related to HOMA-R supporting the hypothesis that SHBG is pathogenetically involved, ameliorating uremic insulin resistance." (PMID 39014506, 2024). "Adiponectin may counteract the inhibitory effect of SHBG by ameliorating insulin resistance." (PMID 38813109, 2024). "Similarly, the levels of the hepatokine sex-hormone-binding globulin (SHBG), binding specifically estrogens and androgens, are lower in patients with metabolic syndrome, and circulating levels of SHBG are considered to be a biomarker for insulin resistance T2D." (PMID 36769005, 2023). "Thus, a low SHBG level may reflect the degree of existing insulin resistance, while androgen excess might impair post‐prandial insulin secretion." (PMID 36484476, 2023). "Thus, a low SHBG level may indicate an advanced degree of existing insulin resistance, while androgen excess might reflect impaired post‐prandial insulin secretion." (PMID 36484476, 2023). "If lower maternal serum SHBG were to reflect insulin resistance, study findings suggest that insulin insensitivity could be occurring in the early second trimester of pregnancies associated with autism even in the absence of subsequent clinical PNMS manifestations." (PMID 37573326, 2023). "Notably, insulin resistance, and consequently hyperinsulinemia, also intensify androgen secretion by theca cells and inhibit the hepatic production of sex hormone-binding globulin (SHBG), hence augmenting the circulating concentration of bioactive free testosterone." (PMID 37109247, 2023). "In addition, insulin resistance reduces the levels of SHBG, resulting in a decrease in TT levels." (PMID 36282472, 2023). "Inflammation and insulin resistance may mediate the link between SHBG and CKD." (PMID 37780623, 2023). "Therefore, one should be cautious about the assumption that SHBG concentrations may replace other markers for assessing insulin resistance." (PMID 35140785, 2022). "The primary mechanism may include insulin resistance and hyperinsulinemia in the patient, which leads to increased ovarian androgen production and hinders the synthesis of sex SHBG in the liver, hence increasing the concentration of free sex hormones when SHBG levels are low." (PMID 36686491, 2022). "Furthermore, SHBG may be upregulated by adiponectin through adenosine 5′-phosphate-activated protein kinase (AMPK) pathways in HepG2 cells, and serum SHBG concentrations may be regulated by metabolic status, such as obesity or insulin resistance." (PMID 34805198, 2021). "Furthermore, as showed by many data in the literature, non-diabetic women with PCOS and with associated insulin resistance showed lower levels of SHBG." (PMID 34886216, 2021). "Because low SHBG is associated with high insulin resistance and high insulin values regardless of weight, low SHBG levels might serve as an indicator of hyperinsulinism and insulin resistance." (PMID 33918160, 2021). "Besides, observational and Mendelian randomization studies have consistently linked lower SHBG levels to an increased risk of insulin resistance and type 2 diabetes, which are important risk factors for CRC, supporting the beneficial role of SHBG in mitigating metabolic perturbations." (PMID 33504335, 2021). "SHBG may affect lipid metabolism by regulating insulin resistance." (PMID 34977197, 2021). "Consequently, this increased insulin resistance translated to reduced SHBG synthesis." (PMID 32992734, 2020).
Insulin resistance (continued). "Lower SHBG usually leads to more free and biologically active androgens in the circulation and might disrupt insulin secretion and pancreatic β-cell function and aggravate MetS and insulin resistance in women with PCOS." (PMID 33101409, 2020). "Taken together, these data imply that low SHBG may be a consequence rather than a cause of insulin resistance." (PMID 33139661, 2020). "However, metformin did not regulate the secretion indexes of fasting insulin, homeostasis model assessment of insulin resistance, sex hormone-binding globulin, high-density lipoprotein cholesterol, total cholesterol, triglycerides, fasting blood glucose, and androstenedione." (PMID 33014044, 2020). "Growing evidence indicates that low circulating SHBG level is an indicator of adiposity and insulin resistance and therefore SHBG may be a clinically useful biomarker for the early identification of children who at risk to develop obesity-related metabolic disorders." (PMID 30925463, 2019). "We also do not have nonfasting measures of insulin resistance in our cohort and therefore could not assess whether insulin levels throughout the day affect the association of SHBG and NAFLD." (PMID 32128321, 2019). "However, subsequent studies have found no direct association between SHBG and insulin or insulin resistance." (PMID 30057912, 2018). "Insulin resistance measured using HOMA-IR has been shown to be inversely associated with bone size, potentially explained by high levels of insulin being inversely associated with sex hormone-binding globulin (SHBG), thus increasing the free concentrations of androgens and estrogens." (PMID 29946974, 2018). "Moreover, low levels of SHBG in adolescence predict adiposity and insulin resistance in adulthood." (PMID 27462374, 2016). "While low SHBG in older children and adults is a recognized marker of insulin resistance and hepatic steatosis, longitudinal studies are needed to determine whether SHBG levels at birth predict metabolic status later in life, and could be used as a marker for early interventions." (PMID 27462374, 2016). "Thus a low level of SHBG might serve as another marker of insulin resistance, and a key factor during the pathogenesis of both PCOS and MetS." (PMID 25223276, 2014). "This could be explained by the fact that obese women already have lower levels of SHBG, resulting in higher levels of bioavailable estrogen, hypoadiponectinemia, insulin resistance, hyperinsuliemia, and high levels of oxidative stress, all of which have been reported to improve in coffee drinkers." (PMID 24666820, 2014). "Whether increased SHBG levels represent a metabolically beneficial process is not clear; however, reduced SHBG levels are associated with insulin resistance and obesity." (PMID 23781319, 2013). "However, to date, the associations of estradiol, testosterone and SHBG with insulin resistance, according to estrogen level, have not been clarified." (PMID 23825975, 2013). "Adiponectin, SHBG- and IGFBP1 are all commonly reduced in people with obesity-related insulin resistance and various lipodystrophies, so these markers are helpful diagnostically in distinguishing those with insulin receptor dysfunction from those with other causes of severe insulin resistance." (PMID 23766565, 2013). "Insulin resistance may be the result of changed body composition, and induces hyperinsulinemia, subsequently stimulates ovarian and adrenal hormonal production and inhibits SHBG production leading to increased testosterone activity." (PMID 21209881, 2010). "Other theories suggest that insulin resistance and increased insulin-like growth factor-1 (IGF-1) promote cell proliferation and higher free estrogen levels through a reduction in sex-hormone-binding globulin." (PMID 40862803, 2025). "This is the first study that estimates the triglyceride–glucose index (TyG) cut-off value, discriminating insulin resistance based on the HOMA-IR value and SHBG level in young Caucasian women with PCOS." (PMID 40430120, 2025).
Insulin resistance (continued). "We also analyzed the probability of insulin resistance assessed on the basis of HOMA-IR values and SHBG levels according to the TyG index using the logistic regression model curves with a 95% confidential interval." (PMID 40430120, 2025). "Our study suggests that the cut-off point for the TyG index in young Caucasian women with PCOS, which discriminates against insulin resistance, is 8.31 (based on both HOMA-IR and SHBG values)." (PMID 40430120, 2025). "Insulin resistance, a core metabolic derangement in PCOS, further contributes to acne by suppressing hepatic SHBG synthesis, thereby increasing free testosterone, and by amplifying IGF-1, mediating follicular inflammation." (PMID 40868844, 2025). "Genes downregulated in SHBG-stimulated adipocytes included LEP, LEPR, FLST3, CRTC2, and ID3, all of which are known to contribute to obesity-induced inflammation and insulin resistance." (PMID 40532849, 2025). "Insulin resistance can lead to hyperinsulinemia, affecting the HPO axis, increases ovarian androgen production, and decreases follicular maturation and sex hormone-binding globulin (SHBG) binding." (PMID 40694958, 2025). "In PCOS with Hashimoto’s thyroiditis (PCOS+HT), insulin resistance also correlates with fasting insulin, HOMA index, BMI, SHBG, and left ovarian volume." (PMID 40161019, 2025). "Our study suggests that the cut-off point for the TyG index, which discriminates insulin resistance based on both HOMA-IR and SHBG values, in young Caucasian women with PCOS, is 8.31." (PMID 40430120, 2025). "A 2022 metanalysis found that Vitamin E supplementation reduced fasting glucose, fasting insulin, homeostasis model assessment of insulin resistance (HOMA-IR), total cholesterol, LDL-cholesterol, triglycerides, total testosterone, and increased SHBG." (PMID 40149685, 2025). "Assessments of insulin resistance (HbA1c, HOMA-IR, ISI), hyperandrogenism (SHBG, FAI), physical activity, and β-endorphin showed significant improvement." (PMID 41210858, 2025). "The aim of this study was to investigate the correlation between serum SHBG, IGF-1 and cortisol with indices of glucolipid metabolism and insulin resistance in patients with GDM and their impact on the development of GDM." (PMID 39876919, 2024). "A focus on the levels of sex hormone-binding globulin (SHBG) and the relationship with insulin resistance in men undergoing chronic hemodialysis was the subject of another research." (PMID 39253627, 2024). "This study examines the role of sex hormone-binding globulin (SHBG) in MAFLD, focusing on its potential as a biomarker and its relationship with insulin resistance." (PMID 39768643, 2024). "Among the prognostic marker candidates, SHBG and IGFBP2 tightly correlated with insulin resistance, while others displayed a weaker correlation." (PMID 39589852, 2024). "Obesity-induced insulin resistance raises circulating insulin growth factor-1 (IGF-1) and reduces sex hormone binding globulin (SHBG)." (PMID 39020272, 2024). "As the hepatic production of both SHBG and IGF-BP1 is downregulated by insulin, their concentrations have been suggested as useful markers of insulin resistance." (PMID 37009276, 2023). "Among the patients diagnosed with PCOS + HT, insulin resistance was found to be significantly correlated with fasting insulin, HOMA index, (BMI), (SHBG) and left ovarian volume." (PMID 36829146, 2023). "Similarly to our observations, decreased SHBG mRNA and protein levels have been previously correlated to lower expression of insulin-associated effectors, namely, IRS-1, IRS-2, PI3Kp85α and GLUT-3 and GLUT-4, and has been further linked to the PI3K/AKT pathway-mediated systemic insulin resistance." (PMID 38146533, 2023). "Androgen excess (characterised by both elevated serum total T concentrations and an increased T‐to‐SHBG ratio, defined as the free androgen index [FAI]) further aggravates insulin resistance and compensatory hyperinsulinaemia, leading to a vicious cycle." (PMID 36484476, 2023).